BDNF (brain derived neurotrophic factor)
Diseases named in the same sentence as BDNF in open-access papers (continued):
Sharing a sentence is not in itself a finding about the gene and the disease.
ischemia (continued). "In a rat model of ischemia, galectin-1 increases brain-derived neurotrophic factor (BDNF) expression in astrocytes." (PMID 36008956, 2022). "It has been reported that under conditions of cellular stress, protein SUMOylation increases, and after ischemia, brain-derived neurotrophic factor (BDNF) levels transiently increase." (PMID 35307349, 2022). "BDNF serves as a mediator of progesterone induced neuroprotection against a variety of insults and unfavorable ambient conditions including ischemia, trauma, and glutamate toxicity." (PMID 36266625, 2022). "We found co-cultured astrocytes can promote the expression of BDNF and proliferation of neuron, and inhibit the cell apoptosis induced by ischemia." (PMID 34852714, 2021). "In conclusion, we demonstrated that caffeine was able to protect RPE cells and RGCs from damage elicited by LPS and ischemia, respectively, showing a key role of BDNF." (PMID 35069225, 2021). "The expression of BDNF in the central nervous system and its influence by ischemia, stress, or hypoglycemia are currently well established." (PMID 32944919, 2021). "Hippocampal BDNF levels tended to be lower in the ischemia group (53.67 ± 12.43 ng/mg) than in the sham group (110.20 ± 41.44 ng/mg, p = 0.29)." (PMID 33920851, 2021). "Brain-derived neurotrophic factor (BDNF) is an important trophic factor that protects neuronal functions following ischemia, trauma, and toxic brain injury." (PMID 34867274, 2021). "Specifically, Irisin release induces BDNF expression in the hippocampus leading to improvement in learning and memory, and protection against injuries such as ischemia, acute stress, and neurodegenerative disorders such as AD." (PMID 33935687, 2021). "The potential protective role of BDNF against ischemia was proved by the BDNF mimetic 7,8-dihydroxyflavone (7,8-DHF)." (PMID 33317180, 2020). "Based on a Pubmed search, a high number of hits were found for the term ‘BDNF’ and ‘ischemia’ (1092)." (PMID 33317180, 2020). "The same effect on the IL-10 level has been demonstrated after intranasal BDNF administration after ischemia." (PMID 32219700, 2020). "Although the present study did not determine this relation, as the first step, we intended to assess the expression of HIF-1α and BDNF/TrkB/CREB proteins following ischemia/reperfusion injury." (PMID 32670026, 2020). "We found a lot more studies from recent years investigating the relation between BDNF and ROS in ischemia." (PMID 33317180, 2020). "Substantial evidence indicates that CREB plays critical roles in the neuronal responses to ischemia, such that activation and overexpression of CREB significantly reduces ischemia-mediated brain injury and increases BDNF and Bcl-2 expression." (PMID 32566081, 2020). "In response to ischemia, astrocytes produce multiple neurotrophic factors to protect neuron, including brain-derived neurotrophic factor, glia-derived neurotrophic factor; nerve growth factor, and vascular endothelia growth factor." (PMID 31167655, 2019). "BDNF expression was increased by the induction of ischemia, while treadmill exercise further increased BDNF expression in the ischemic gerbils." (PMID 30210424, 2018). "Recent studies demonstrate that post-ischemia treatment with exogenous BDNF not only exerts neuroprotection but also induces neuronal regeneration." (PMID 29801454, 2018). "BDNF levels were enhanced by both the ischemia and either a single 30 min walk or 12 h voluntary run." (PMID 30210424, 2018). "Other cell types, such as CD68+ microglia, and NeuN+ neurons, are partly responsible for production of BDNF, even after the induction of ischemia." (PMID 30405724, 2018). "Ischemia-induced accumulation of Ly6C+ cells was localized in the ischemia core cortex and the surrounding areas, the same region where BDNF+ cells resided." (PMID 30405724, 2018). "We have shown that in the ipsilateral ischemia core cortex, Iba-1+ cells are one of the main sources for the production of BDNF." (PMID 30405724, 2018).
ischemia (continued). "BDNF is a downstream neuroprotective target of CREB that is involved in neuronal survival after ischemia, and it is a neurotrophic factor that can phosphorylate CREB." (PMID 28408940, 2017). "The most commonly evaluated trophic factors in experimental models of ischemia include BDNF, GDNF, EGF, FGF-2, VEGF, and IGF-1." (PMID 26607630, 2016). "In the ASC-ischemia group, the BDNF level was significantly increased compared to the vehicle-ischemia group." (PMID 24592394, 2014). "In the vehicle-ischemia group, the BDNF level was significantly decreased compared to the sham group and the BDNF level from L5-L6 spinal cord homogenates was 65 pg/mg protein." (PMID 24592394, 2014). "It is worthy to note that F3.Olig2-Shh cells express considerably high level of BDNF which is known for it’s significant neuroprotective function in neurodegenerative diseases, ischemia and brain injury." (PMID 24844281, 2014). "In the present study, the BDNF levels were higher in the ventral horn of spinal cord in ASC-ischemia group than those in the vehicle-ischemia group." (PMID 24592394, 2014). "Treadmill exercise prior to experimental ischemia improved motor performance and upregulated BDNF and TrkB expression in the contralateral hemisphere." (PMID 24818146, 2014). "There are two types of BDNF: pro− and mature BDNF, mature BDNF is crucial in the protection of the neonatal or developing brain from ischemia injury." (PMID 25386685, 2014). "NPAS4 combines with ARNT2 to regulate the expression of BDNF, with consequent neuroprotective effects on brain injury and ischemia." (PMID 24669275, 2014). "BDNF increases neurogenesis, improves memory acquisition and has anti-apoptotic and anti-inflammatory effects, as well as protecting against hypoxia/ischemia-induced brain injury." (PMID 25551197, 2014). "After 1-hr ischemia and 24-hrs of reperfusion, BDNF expression remained at a similar level as that of the prior ischemia in the ipsilateral cortex." (PMID 23844255, 2013). "BDNF is an important neuroprotective factor that has been proven to increase the tolerance of neurons against the ischemia in both in vitro and in vivo studies." (PMID 23844255, 2013). "The activation of NF-κB induced by BDNF protects cells from a variety of damages, including the serum starvation, glutamate toxicity and ischemia." (PMID 21490702, 2010). "The comparison of the groups based on neurological deficit scores demonstrated that the neurological deficit scores of the Control and Sham CI groups were significantly lower when compared to the ischemia and BDNF groups between the 1st and 7th days (p < 0.05)." (PMID 38520223, 2024). "While there are few studies of pediatric ischemic injury after cardiac arrest, these initial studies suggest neuroprotective responses of BDNF in the post-ischemia stages of recovery and potentially key age-related differences for BDNF in the brain post injury." (PMID 38397427, 2024). "However, ICV BDNF treatment reduced the cleaved caspase‐3 protein level and the number of positive cells, which increased after ischemia in the penumbra (p < 0.05)." (PMID 38520223, 2024). "miR-15a is a target of PPAR- transrepression directly regulates BCL-2 and contributes to PPAR-mediated vascular protection against ischemia-like insults.67miR‐15a regulates oxygen-glucose deprivation/reperfusion (OGD/R)‐induced neuronal injury by targeting BDNF." (PMID 40190672, 2024). "Animal studies show that BDNF can also be used to improve ischemia-related recovery." (PMID 37583548, 2023). "In addition, brain-derived neurotrophic factor protein levels in the ischemia-treated group with 50 mg/kg of Alpinia katsumadai seeds were much higher than those in the ischemia-treated group." (PMID 37299465, 2023). "Evidence also exists showing that the BDNF synthesized by microglia is present in various regions of the CNS during the course of various neurological disorders such as traumatic injury and ischemia." (PMID 37888721, 2023).
ischemia (continued). "Our present study also proves that stress causes pathological and morphological changes in the hippocampus, which is consistent with prior studies that show that several brain related issues, such as stress, seizure, ischemia, and hypoglycemia, alter BDNF expression in the central nervous system." (PMID 35600855, 2022). "Additionally, to investigate the healing effect of hBM-MSCs, the cerebral infarction lesion was stimulated by PEMF in the mouse ischemia model, after which the expression levels of Neuro D1, NF, and BDNF were evaluated via immunohistochemical staining." (PMID 35163096, 2022). "We speculated that during ischemia, increased BDNF expression could reduce synaptic abundance of GABAARs via PIAS-3–mediated gephyrin modification at K148 and K724 residues." (PMID 35307349, 2022). "Additionally, with tacrine administration, the BDNF level was equal to that in the sham group (ischemia + saline: 52.76 ± 15.03 ng/mg, ischemia + tacrine: 90.27 ± 31.52 ng/mg, p = 0.68)." (PMID 33920851, 2021). "Another study analyzed the function of BDNF on miRNA profiling in human endothelial progenitor cells (EPC) as these cells show protective effect against cerebral vascular integrity in brain endothelium after ischemia." (PMID 32944919, 2021). "Blood BDNF levels also tended to be lower in the ischemia group (75.27 ± 8.66 pg/mL) than in the sham group (91.67 ± 10.57 pg/mL, p = 0.59), and this tendency was more pronounced with tacrine administration (ischemia + saline: 75.03 ± 17.27 pg/mL, ischemia + tacrine: 90.40 ± 29.07 pg/mL, p = 0.79)." (PMID 33920851, 2021). "However, only a few articles were found showing direct evidence between BDNF and ROS-induced regulation of ischemia." (PMID 33317180, 2020). "Moreover, BDNF levels were significantly decreased in the hippocampus 24 h after ischemia/reperfusion in CD- and PDD-fed gerbils, and significantly lower levels (67.5% of CD-fed gerbils) of BDNF were found in the PDD-fed gerbils 24 h after ischemia." (PMID 32759679, 2020). "However, boosting of neurotrophic signaling after ischemia is challenged by downregulation of BDNF high‐affinity receptor, full‐length tropomyosin‐related kinase B (TrkB‐FL), due to calpain‐degradation, and, secondarily, regulated intramembrane proteolysis." (PMID 31273936, 2019). "Although MSC infusion reduced the total number of Ly6C+ cells in the brain, MSC treatment nevertheless enhanced the total number of BDNF+/Ly6C+ cells and increased the percentage of BDNF-producing cells among the infiltrated monocytes/macrophages in the infarct area two days after ischemia onset." (PMID 30405724, 2018). "As results, C·H-astrocytes upregulated neurotrophic factors NGF and BDNF each 2.83 and 1.91 times those H-astrocytes, indicating C-Pc pre-treatment could contribute to recover the injury after ischemia and reperfusion." (PMID 26399322, 2015). "Among two forms of extracellular BDNF, pro- and mature BDNF, mature BDNF is essential in protection of neonatal or developing brain from ischemia injury as well as neuronal cells, whereas pro-BDNF may induce neuronal death." (PMID 26122524, 2015). "While most of these studies examined infarct formation or neurological recovery in the early period following ischemia, a more recent study demonstrated that transplantation of neural stem cells (NSCs) overexpressing BDNF improved neurological function as late as 12 weeks after MCAO." (PMID 24818146, 2014). "The expression of the TrkB receptor in astrocytes provided a clue concerning the BDNF immunolabeling results and suggested that the TrkB receptor in astrocytes “traps” extracellular BDNF released by endothelial and/or neuronal cells following ischemia." (PMID 23383048, 2013). "However, BDNF can be released by glial cells (astrocytes and oligodendrocytes,) and ischemia can modify BDNF expression by activating glial cells." (PMID 22792408, 2012).
ischemia (continued). "However, conversely, enhanced long-term AAV-mediated BDNF expression in the hippocampus was shown to inhibit neurogenesis following ischemia in rats." (PMID 23346046, 2012). "Our data suggested that BDNF might protect brain from ischemia through upregulating local IL10 in brain." (PMID 21490702, 2010). "Furthermore, engineered MSCs with the BDNF gene effectively promote neural differentiation and also protect against injury in transected spinal cord or ischemia animal models." (PMID 20462460, 2010). "Animal studies demonstrate a neuroprotective effect of intravenous BDNF–gene-modified human mesenchymal stem cells injection in reducing infarct size, as well as intraventricular BDNF pretreatment preserving pyramidal cell integrity in the hippocampus post-ischemia." (PMID 40658687, 2025). "However, ICV BDNF administration significantly reduced the post‐ischemia infarct area (p < 0.05)." (PMID 38520223, 2024). "The mechanisms, by which atypical antipsychotics may exert neuroprotection, include neurogenesis, protection against toxicity, ischemia, and insults or the upregulation of neurotrophic factors such as brain-derived neurotrophic factor (BDNF) and nerve growth factor (NGF)." (PMID 35887056, 2022). "As a neurotrophic factor, the BDNF exerts essential roles in the in vivo development of motor neurons, the survival of adult motor neurons, survival of pathological motor neurons, and even the regeneration of axons and protection of brain tissues after ischemia." (PMID 36065265, 2022). "Finally, using oxygen–glucose deprivation as an in vitro model for ischemia, we show that BDNF–tropomyosin-related kinase B signaling negatively impairs clustering of the main scaffolding protein at GABAergic postsynapse, gephyrin, whereby reducing GABAergic neurotransmission postischemia." (PMID 35307349, 2022). "Importantly, BDNF treatment significantly inhibited miR-433 and induced miR-181c concentration, which might improve regenerative effect of EPCs in ischemia." (PMID 32944919, 2021). "To determine whether BDNF modulates the ischemia-induced migration of neuroblasts, we monitored neuroblast migration in the injured striatum of acute slices before and after the bath-application of BDNF or TrkB-Fc in order to scavenge endogenous BDNF." (PMID 23383048, 2013). "The current study found that administering Prdpn had a neuroprotective impact and improved functional recovery in ischemia-reperfusion models of spinal cord injury by increasing GDNF and BDNF spinal expression levels." (PMID 39937253, 2025). "In models of ischemia, MSC injections increased the numbers of RGCs and the levels of brain-derived neurotrophic factor (BDNF), ciliary neurotrophic factor (CTNF), and the fibroblast growth factor (bFGF)." (PMID 36496979, 2022). "The authors conjugated BDNF to the transferrin receptor antibody OX26 and demonstrated restoration of CA1 region in hippocampus after ischemia in rats after i.v. delivery of PEG-BDNF-OX26." (PMID 34149364, 2021). "One of the most extensively studied compounds that imitates the function of BDNF is 7,8-dihydroxyflavone (7,8-DHF), a small molecule TrkB agonist that protects neurons from kainic acid-induced toxicity and experimental ischemia." (PMID 32399020, 2020). "In ischemia/reperfusion rats, Wharton’s jelly-derived mesenchymal stem cells obviously increased gene expression of GDNF and BDNF and improved the functional learning and memory." (PMID 32265642, 2020). "BDNF can suppress TNF-α and its mRNA expression, this exacerbating ischemia-induced injury, while it increases IL-10 and its mRNA expression, which play an anti-inflammatory neuroprotective role." (PMID 30622436, 2018). "Both brain-derived neurotrophic factor (BDNF) and nerve growth factor (NGF) have been reported to be neuroprotective in the middle cerebral artery occlusion (MCAO) rat model of ischemia." (PMID 30581534, 2018).
ischemia (continued). "Borlongan and colleagues have shown that 3 days after intravenous administration of human umbilical cord-blood cells, there was an increased expression of BDNF, GDNF, and NGF in the rat brain after ischemia, compared to control animals." (PMID 26607630, 2016). "In our study, the BDNF protein and NT-3 mRNA levels of the BNG-1 group were significantly higher than those of the saline group at 7 d after ischemia." (PMID 25506838, 2014). "BDNF and TGF-β1, the growth factors located in extracellular matrix, both play a comprehensive role in neuroprotection after ischemia through ERK pathway or SMAD family, respectively as the important extracellular signals." (PMID 23049867, 2012). "Lamina cribrosa cells and ONH astrocytes respond to conditions that mimic ONH ischemia by increasing NGF, BDNF and NT-3 protein expression and NGF secretion." (PMID 15579199, 2004). "Importantly, the change in pro-BDNF level was found only in IVH, while the pro-NGF level was changed as well as in ischemia and asphyxia." (PMID 40003962, 2025). "Furthermore, salidroside elevated the mRNA expression and protein concentration of BDNF and NGF in ischemia periphery area, as well." (PMID 39090706, 2024). "Moreover, metformin up-regulated the brain-derived neurotrophic factor (BDNF) expression and increased phosphorylation levels of AMP-activated protein kinase (AMPK) and cAMP-response element binding protein (CREB) in the ischemia penumbra." (PMID 35431946, 2022). "Huang (2018) also showed significant increases of BDNF expression and BDNF receptors in DRG of endometriosis‐like diseases those are accompanied by complex mechanisms of pain (increased cytokines, peripheral and central nerve sensitization, and ischemia)." (PMID 34806344, 2021). "Also in vivo, HA has been proved to persistently increase NGF, BDNF and TGF-β1 mRNA levels in cerebral cortex and hippocampus of mice injured with ischemia and reperfusion." (PMID 34526893, 2021). "Furthermore, upregulation of neurotrophic and growth factors, such as the brain-derived neurotrophic factor (BDNF), induced by long-term DR has been shown to reduce neuronal injury after ischemia." (PMID 33271979, 2020). "We hypothesized that CA produces neuroprotection on NVU against ischemia through the BDNF-TrkB-PI3K/Akt signaling pathway and the BDNF-TrkB-MAPK/Erk signaling pathway." (PMID 33101581, 2020). "Our present result showed that BDNF immunoreactivity recovered well with significant attenuation of immediate early genes and reactive astrocytosis after ischemia in the 3 pre-treatment groups when compared with no treatment group." (PMID 26760774, 2016). "In a similar study, BDNF did not reduce infarct volume but still resulted in greater functional recovery following ischemia compared to controls." (PMID 24818146, 2014). "These current results strongly suggest that upregulation of neuronal BDNF and vascular SDF-1α after EA pretreatment might be an important protective mechanism of tolerance against ischemia." (PMID 23356671, 2013). "In addition to BDNF, GDNF was found to protect neuronal damage against ischemia, drug abuse, and pain." (PMID 23304227, 2012). "Though most studies find that the spike in BDNF expression in the brain attenuates quickly following ABI, with some studies showing a return to control concentrations by 24 h to one week post injury, changes in BDNF expression can continue for up to 20 weeks post ischemia." (PMID 38397427, 2024). "Hence, we suspected the elevated BDNF expression in the AMI group might be related to rapid endothelial cell proliferation and revascularization after ischemia." (PMID 38145212, 2023). "Taken together, these findings suggest that ischemia–reperfusion of the limbs increases BDNF expression in the brain regardless of whether it occurs during the pre-, per-, or post-period." (PMID 36750711, 2023).